EPO (erythropoietin)
Diseases named in the same sentence as EPO in open-access papers (continued):
Sharing a sentence is not in itself a finding about the gene and the disease.
cancer (288 papers, 1993 to 2026). A tumor composed of atypical neoplastic, often pleomorphic cells that invade other tissues. "Multivariable Cox regression revealed that higher EPO (HR 1.26; 95% CI 1.07-1.47; p = 0.005) was associated with increased overall cancer risk, while elevated hepcidin levels were associated with a lower risk (HR 0.88; 95% CI 0.80-0.96; p = 0.006)." (PMID 42100998, 2026). "A recent, provocative, experimental study published by Chiu and colleagues stands out in the overall, blurred context of EPO and cancer progression risk." (PMID 41375075, 2025). "The understanding of the benefit–risk balance of recombinant-EPO (r-EPO) has deepened, and greater caution is now required before initiating r-EPO treatment in cancer patients." (PMID 41375075, 2025). "The same Cochrane showed a significant increased risk to develop thrombocytopenia in erythropoietin-treated cancer patients." (PMID 30294279, 2018). "Like other cancer types, co-expression of EPO and EPOR has been reported in NSCLC and was associated with poor survival of NSCLC patients." (PMID 29137269, 2017). "A meta-analysis based on 25 randomised controlled trials including 3,069 cancer patients showed that the use of erythropoietin significantly reduced the relative risk of red blood cell transfusion (RR 0.67, 95% CI: 0.62, 0.73)." (PMID 21331363, 2010). "The causation of thromboembolic events in patients receiving erythropoietin growth factors is complex because of the increased baseline risk of thrombosis associated with chemotherapy and with cancer in general." (PMID 18231643, 2008). "Recombinant human erythropoietin (rHuEpo) has recently become available for the treatment of chronic anaemia, including that associated with cancer." (PMID 8398699, 1993). "Erythropoietin-producing human hepatocellular receptors (EPHs) constitute the largest known family of tyrosine receptors, and, along with their ligands, EFNs, regulate key physiological processes and are implicated in cancer pathogenesis." (PMID 41516312, 2025). "Other causes of renal anemia include nutritional deficiencies such as iron, folic acid, and vitamin B12; other concomitant chronic inflammatory states like diabetes and cancer; and another major cause being higher circulating levels of uremia-induced inhibitors of EPO." (PMID 41179057, 2025). "However, there is uncertainty regarding the potential risks associated with EPO derivatives in cancer patients." (PMID 41375075, 2025). "Our study indicates that the serious risks associated with the use of erythropoietin-stimulating agents (ESAs) in anemic cancer patients may be attributed to their ability to promote drug-tolerant cancer cells through the senescence program." (PMID 37543610, 2023). "To explore convergent mechanisms that may underlie the pleiotropic effects of Pinus koraiensis leaf oils, we first integrated targets associated with antioxidant, anti-inflammatory, cancer cell growth inhibitory, and antimicrobial activities reported for EPO and SPO." (PMID 41598205, 2025). "The systemic inflammatory response in cancer patients contributes to reduced iron metabolism, diminished response to erythropoietin, and decreased red blood cell survival, which may explain the symptoms and clinical signs in cancer patients: weight loss, anorexia, and cancer-related anemia." (PMID 27658208, 2016). "Therefore, we speculated that the described overexpression of EPO-EPOR in several types of carcinoma could be at least in part due to the concomitant loss of miR-125b." (PMID 24165569, 2013). "Globally, these findings bring an important contribution to the still open questioning regarding the multifaceted aspects relative to the EPO use in cancer therapy." (PMID 41375075, 2025). "We also reviewed the safety concerns related to r-EPO use in cancer care, with particular attention to the ongoing debate about its potential negative impact on overall patient survival." (PMID 41375075, 2025).
cancer (continued). "As a significant additional benefit of r-EPO administration in cancer patients, there is the well-characterized clinical capacity to reduce fatigue." (PMID 41375075, 2025). "Pediatric cancers often have developmental origins, making the role of EPO/EPOR even more intriguing." (PMID 38542288, 2024). "This suggests that besides its role in erythropoiesis, hypoxia-induced EPO acts as a survival factor for pediatric cancer cells by promoting angiogenesis and inhibiting apoptosis." (PMID 38542288, 2024). "Mechanisms linking elevated RDW to poor prognosis in cancer include inflammation suppressing erythropoietin activity and increased oxidative stress reducing red cell lifespan and stability." (PMID 39385181, 2024). "Lodish, who was also the legal advocate for Amgen in patent disputes, said the FDA did not make any decision on an eventual restriction of the use of EPO in cancer patients for a long time." (PMID 38672425, 2024). "Another example of a non-cancer drug that has failed clinical testing in combination with RT is EPO." (PMID 39886153, 2024). "The big booster of EPO sales was represented by cancer patients and by the personal use of normal individuals." (PMID 38672425, 2024). "Based on the paper by Dr. Elliott and on the testimony of Dr. Lodish, who was also the legal advocate for Amgen in patent disputes, the FDA did not take any decision on an eventual restriction of the use of EPO in cancer patients for a long time." (PMID 38672425, 2024). "It was the large number of cancer patients, including those with breast cancer, who soon became the biggest EPO users." (PMID 38672425, 2024). "The convergence of HIF-1α and EPO/EPOR signaling further underscores their complex influence on cancer progression." (PMID 38542288, 2024). "First discovered during investigations of erythropoietin production regulation, HIFs influence physiological and pathological processes, including development, inflammation, wound healing, and cancer." (PMID 38312838, 2024). "It was the misuse of EPO in cancer patients that raised the strongest and more controversial concerns." (PMID 38672425, 2024). "The routine use of erythropoietin stimulating agents in cancer is controversial, with limited data in children with cancer." (PMID 35792092, 2023). "EPHA8 belongs to the erythropoietin-producing hepatocellular receptor family of transmembrane receptor tyrosine kinases, which are dysregulated in various cancers." (PMID 37444464, 2023). "Published data have also suggested higher mortality rates among cancer patients treated with erythropoietin stimulating agents." (PMID 36314077, 2023). "Due to its proliferative, antiapoptotic, and angiogenesis-stimulating activity, the use of erythropoietin in cancer patients is controversial." (PMID 37894821, 2023). "In contrast, only 3 pathways were upregulated in the top 22 pathways affected by KZR-616: erythropoietin signaling, valine degradation, and PD-1/PD-L1 cancer immunotherapy." (PMID 36969170, 2023). "The notion that some tumors express functional EPOR is based on the binding of EPO to EPOR in cancer cells in vitro and in vivo." (PMID 36052260, 2022). "Exercise can also be combined with erythropoietin (EPO) to investigate the effects on muscle alterations in cancer cachexia." (PMID 36499157, 2022). "Metastatic spreading of cancer cells was evaluated by assessing the expression of human erythropoietin (EPO) and HLA class I histocompatibility antigen, alpha chain G (HLA‐G) in the lungs of mice injected with H/OSM or H/pCMV6 cells." (PMID 35064579, 2022). "EPOR-deficient A549 tumors had lower pAKT levels than control tumors and AKT is often phosphorylated by EPO/EPOR in other (cancer) cells, supporting their growth and regulating mitochondrial biogenesis." (PMID 36052260, 2022).
cancer (continued). "BCL-RAMBO is one of the seven pro-apoptotic genes with expression levels that decrease in human LU-HNSCC-7 squamous cell carcinoma xenografted in nude mice receiving erythropoietin, which is used to treat anemia in cancer patients." (PMID 36589739, 2022). "Cancer-induced inflammation leads to inhibited response to erythropoietin, reduced iron release from reticuloendothelial macrophages, and shortened red blood cell survival." (PMID 34879841, 2021). "Studies were obtained using the following keywords: “STAT5” or “erythropoietin” or “erythropoietin receptor” and “erythropoiesis” or “cancer cell” or “normal cell” or “signaling”." (PMID 34281163, 2021). "The items extracted from each study included study-year, type of recombinant erythropoietin, number of patients in treatment and control/placebo group, duration of treatment, concomitant treatments, and cancer types." (PMID 34527499, 2021). "Nevertheless, further research must be performed to prove the contribution of AKT, MAPK, and their cooperation regarding the EPO/EPOR or constitutive EPOR in cancer cells." (PMID 34299300, 2021). "Nevertheless, we can conclude that EPO signaling has several different features in cancer cells compared to erythroid tissue." (PMID 34299300, 2021). "While EPO signaling during erythropoiesis plays a main role in differentiation and proliferation, in cancer cells the signaling refers more to anti-apoptotic cell survival and migration activity." (PMID 34299300, 2021). "The score is calculated based on cancer type, Plt count, Hb level, erythropoietin drug use, WBC count, and BMI." (PMID 31823160, 2020). "In recent years, however, are growing doubts about the appropriateness of the use of erythropoietin in cancer patients in the view of reported decreased survival of cancer patients treated with EPO." (PMID 32748255, 2020). "EPO directly increases the vascular angiogenesis of cancer cells and EPO increases the macrophage secretion of VEGFC, then increases lymphangiogenesis and nodal metastasis." (PMID 32908942, 2020). "This is probably related to the high doses of EPO and the presence of EPO-R receptors on the surface of certain cancer cells." (PMID 32748255, 2020). "Animal results show that EPO-releasing cancer trap attracted large number of circulating PCa and significantly reduced cancer spreading to other organs compared with controls." (PMID 32157115, 2020). "EPO increases the expression of EPOR in cancer cells, thereby increasing cancer cell growth and metastasis." (PMID 32908942, 2020). "The anti-cancer mechanism of action of EPO-TAMNLC is via the reduction cancer cell proliferation, inducing in vitro apoptosis and cancer cell cycle arrest at the G0/G1 phase." (PMID 31291309, 2019). "The human and experimental studies have revealed that EPO and EpoR can co-express in a diversity of human malignancies and the EPO/EpoR signaling is involved in cancer cell proliferation, inhibition of apoptosis, and invasiveness." (PMID 31217907, 2019). "To date, conclusion that EPO/EPO-R promotes endothelium-dependent angiogenesis in cancer has been well established." (PMID 30915348, 2019). "It is also postulated that uptake of EPO-TAMNLC by cancer cells is through EpoR-mediated endocytosis, otherwise known as clathrin-mediated endocytosis." (PMID 31291309, 2019). "They provide an experimental model to investigate the effect of EPO on cancer cells exposed to chemotherapy." (PMID 30622244, 2019). "KIAA0101 induced by erythropoietin, promoted cancer proliferation and migration, and higher expression of KIAA0101 was associated with a poorer prognosis in RCC." (PMID 29928475, 2018). "At body temperature, thermosensitive nanoparticles release erythropoietin to lure metastatic cancer cells." (PMID 35548629, 2018). "The use of preoperative recombinant human erythropoietin in cancer patients appears to be safe, although previous studies have associated its use with the progression of disease and mortality." (PMID 29743022, 2018).
cancer (continued). "Unfortunately, compared with other cancer types, very few studies have been conducted regarding the role of endogenous or exogenous EPO/EPOR in HCC." (PMID 29238266, 2017). "Considering the incidence and severity of fatigue in cancer patients on chemotherapy, it is to be hoped that erythropoietin will be approved for clinical use in the Japanese oncology field." (PMID 28386794, 2017). "The cellular mechanism of the action of EPO in cancer cells in contrast, appears not only potentially different from the one described in hematopoietic cells but also seems to vary among cancer cell types and even within cell types." (PMID 28415825, 2017). "Recently, EPO has drawn much attention in the field of cancer treatment, because anemia is a common complication in cancer patients, especially those who receive chemotherapy." (PMID 29238266, 2017). "Clinical studies have indicated decreased survival in some groups of cancer patients treated with EPO." (PMID 28418910, 2017). "Several clinical-trials even indicated impaired disease control or decreased survival in cancer patients treated with EPO, such as in head and neck cancer patients." (PMID 29238266, 2017). "Due to its proliferative, antiapoptotic and stimulating angiogenesis activity, use of erythropoietin in cancer patients is controversial." (PMID 27543111, 2016). "Several clinical trials have addressed the effects of one of the EPO/ESA treatments on disease control in cancer patients on co-temporal anti-cancer therapy, such as chemotherapy, radiotherapy, neoadjuvant therapy, and surgery." (PMID 25426117, 2014). "There has been much discussion of EPO use in cancer patients, and several professional and regulatory organizations and authorities have issued various guidances." (PMID 25426117, 2014). "This is followed by a more detailed presentation of both pre-clinical and clinical data that demonstrate EPO’s diverse actions on cancer cells as well as possible receptors involved in the response of cancer cells to EPO/ESA therapy." (PMID 25426117, 2014). "This study reaffirmed the importance of EPO as a molecular mediator produced by the liver during the process of chronic hepatic injury and regeneration in its progression to cancer." (PMID 23052842, 2013). "In fact, the EPO expression in cholangiocytes grew in a time-dependent manner and became particularly elevated in the hyperplastic bile ducts of the cancer tissue, where it was, however, possible to individuate isolated clusters of negative bile ducts." (PMID 23052842, 2013). "Using commercial tissue microarray (TMA) of a variety of cancers and benign tissues, EPO and EPO receptor immunohistochemical staining was performed." (PMID 24004818, 2013). "Is the key regulator in the production of RBC, methylation of the promoter section of EPO is identified in many cancers including lung, breast liver etc. though its prognostic value efficiency is not reported." (PMID 24369052, 2013). "The existence of the EPO/EpoR signaling pathway has been recently observed in a wide range of tumors and cancer cell line, but its role and true function in the context of cancer biology are still a matter of controversy and currently under investigation." (PMID 23052842, 2013). "Apart from counteracting VEGF-related IL-2 resistance, EPO controlled cancer growth and reduced the toxicity of IL-2." (PMID 23305401, 2013). "While the hypoxic trigger of EPO is a major problem in cancer biology in general, this is of special significance in the case of RCC, because of the direct regulation of EPO by HIF." (PMID 23305401, 2013). "The roles of EPO had been well documented in erythrocytopoiesis, but its clinical relevance in carcinoma remained controversial and deserved for further investigations." (PMID 23825635, 2013). "Human recombinant EPO has already demonstrated benefits in cardiac, cancer, orthopedic, and bloodless surgery." (PMID 22353604, 2012).
cancer (continued). "This reflects practices which are no longer recommended following the recent clinical practice guidelines regarding EPO administration in cancer patients." (PMID 22950685, 2012). "This was borne out in the TREAT study where the incidence of cancer deaths was higher in the EPO-treated group." (PMID 21943500, 2011). "A meta-analysis based on 14 randomised controlled trials including 2,347 cancer patients, with haematologic response to treatment with erythropoietin defined as an increase in Hb of at least 2 g/dL unrelated to transfusion, reported response rates of 9–70%." (PMID 21331363, 2010). "This is the case with blood transfusion in older people, or when haemoglobin levels rise upon treatment with erythropoietin in cancer or renal disease." (PMID 18201374, 2008). "Cancer patients who are anemic have been shown to have a blunted response for production of endogenous erythropoietin growth factor." (PMID 18231643, 2008). "The use of erythropoietin in anaemic cancer patients has been studied to reduce the need for transfusions and to improve the quality of life (QOL)." (PMID 14647149, 2003). "Recombinant human erythropoietin (rHuEPO) is an effective therapy to increase haemoglobin values in over half of anaemic cancer patients receiving concurrent chemotherapy." (PMID 11308272, 2001). "The purpose of this study was to determine the safety, efficacy and impact on quality of life of recombinant human erythropoietin (r-HuEPO) for cancer patients undergoing radiotherapy (RT)." (PMID 9667681, 1998). "Additionally, EPO can indirectly promote cancer progression by inhibiting chemotherapy-induced cell death, thereby contributing to treatment resistance." (PMID 41602576, 2026). "Although HBSP has shown clinical efficacy in improving neuropathy associated with sarcoidosis, clinical trials for other EPO-derived peptides remain scarce, possibly due to concerns that activation of the EPOR pathway may also contribute to cancer progression." (PMID 41602576, 2026). "Interestingly, EPO is known to increase GABA currents suggesting an implication of GABA neurotransmitter in the adverse effect of EPO in cancer development." (PMID 40457205, 2025). "The network- and pathway-based analysis indicate that EPO and SPO- specific constituents converge on a shared set of multifunctional genes enriched in inflammatory, oxidative-stress, and cancer-associated signaling pathways, with NOS2 emerging as a common putative core target." (PMID 41598205, 2025). "This evolving body of evidence calls for an objective reassessment of EPO’s dual nature as both a therapeutic ally and a potential oncological threat, in order to bring more caution around decision-making in the current era of strongly evolving cancer care." (PMID 41375075, 2025). "More recent meta-analyses on the existence or not of a risk of unfavorable cancer evolution under r-EPO underline this climate of doubt." (PMID 41375075, 2025). "Also, anemic cancer patients were shown to have lower erythropoietin (EPO) levels than expected, indicating a reduced EPO response." (PMID 40867262, 2025). "Our primary research goal is to ascertain whether a NOP protocol can increase reticulocyte counts, indicating a rise in EPO production, among cancer patients undergoing abdominal surgeries." (PMID 38978080, 2024). "By preventing the apoptosis of cancer cells, EPO might inadvertently help and promote the survival and proliferation of malignant cells." (PMID 39355466, 2024). "EPO has been widely used to overcome hypoxia in patients with cancer." (PMID 39474425, 2024). "The debate was: do cancer cells express EPO-R and proliferate at pharmacological doses of EPO?" (PMID 38672425, 2024). "In a meta-analysis of randomized trials of recombinant human erythropoietin and mortality in cancer patients, ESAs increased mortality in all cancer patients, and a similar increase in mortality may occur in chemotherapy patients." (PMID 38967734, 2024).